FGF19 (fibroblast growth factor 19)
Diseases named in the same sentence as FGF19 in open-access papers (continued):
Sharing a sentence is not in itself a finding about the gene and the disease.
Insulin resistance (continued). "Since fatty liver disease and insulin resistance are known factors that are able to blunt FGF-19 secretion, an individual metabolic constellation might affect the correlation between bile acids and FGF-19 release." (PMID 26863103, 2016). "In addition, adults with NAFLD and insulin resistance have been previously found to have an impaired response to FGF19." (PMID 27203081, 2016). "To assess the ability of central FGF19 to improve glucose intolerance in Ay mice, we used the same daily FGF19 icv injection protocol used above and that successfully improved glucose intolerance and insulin-resistance in HFD-fed and ob/ob mice." (PMID 24567901, 2014). "In this context, we wanted to assess whether central FGF19 signaling was effective to improve insulin-resistance and hyperglycemia in obese mice." (PMID 24567901, 2014). "In addition to the effects in insulin resistance and glucose metabolism, FGF19 increases serum BHB levels even in Fgfr4 KO mice, like FGF21." (PMID 21437243, 2011). "In particular, while our findings suggest potential associations between cBAs, FGF-19, and indices of insulin resistance such as HOMA-IR, the study design does not allow us to establish whether these relationships are causal." (PMID 41169463, 2025). "However, the relationship between fasting cBAs, FGF-19, and insulin resistance—as estimated by HOMA-IR—remains unclear." (PMID 41169463, 2025). "Moreover, the Chinese patients revealed a negative association between FGF19 and insulin resistance, which supported the previous findings." (PMID 23940810, 2013). "In our study, serum FGF19 levels were significantly reduced following acupuncture, implicating modulation of the FXR signaling pathway in alleviating insulin resistance in PCOS patients." (PMID 41514462, 2026). "Further regulatory network analysis revealed that insulin resistance and sensitivity pathways were modulated through key genes, including IRS2, CPE, ADRB2, NR4A3, and FGF19." (PMID 40969325, 2025). "Fasting blood samples were collected to assess serum levels of Orexin A, PBP4, and FGF19, as well as to calculate HOMA-IR as a measure of insulin resistance." (PMID 40859577, 2025). "However, when the mutually-adjusted model was applied the association with FGF-19 remained, suggesting that FGF-19 could be linked to pathways involved in the control of insulin resistance, independent of fasted circulating bile acids concentrations." (PMID 41169463, 2025). "FGF19 treatment restored PA‐ and HFD‐induced hyperglycaemia, impaired glucose tolerance and insulin resistance (IRS‐1, GLUT‐4) and mitigated the PA‐ and HFD‐induced decrease in FNDC‐5/irisin expression." (PMID 33751819, 2021). "The low HOMA-IR group has significantly higher levels of Orexin A, PBP4, and FGF19 compared to the high HOMA-IR group (P-values: .02.04, and .01, respectively), indicating a negative association with insulin resistance." (PMID 40859577, 2025). "Furthermore, overexpression of the Fgf15 human ortholog, FGF19, can mitigate HFD-induced glucose intolerance and insulin resistance in mice, which is similar to the ameliorative effects of curcumin on HFD-induced GLMDs in mice." (PMID 36348361, 2022). "Furthermore, the inhibition of AMPK, SIRT‐1 and PGC‐1α reversed the beneficial effects of FGF19 on mitigating PA‐ and HFD‐induced lipid droplet accumulation and insulin resistance." (PMID 33751819, 2021). "This nutraceutical combination appears to be safe also in terms of glucose metabolism, since no changes were observed regarding insulin resistance and FGF19 and FGF21 levels." (PMID 30795775, 2019). "First, the serum concentrations of FGF19 were lower in N-DM group and even lower in DM group than in NC group regardless of the degree of insulin resistance." (PMID 31572498, 2019).
Insulin resistance (continued). "Orexin A, PBP4 and FGF19 levels are significantly higher in the low HOMA-IR group compared to the high HOMA-IR group, with P-values of 0.02, 0.04, and 0.01, respectively, indicating a negative association with insulin resistance." (PMID 40859577, 2025). "They suggested that reduced FGF19 expression in women with GDM may be related to the pathophysiology of the disease, while elevated FGF21 expression could result from a compensatory response to the insulin resistance observed in GDM." (PMID 38139126, 2023). "Further, the level of fibroblast growth factor 19 (FGF19), as a downstream molecule of intestinal FXR signal, is significantly decreased in GDM and exhibits a negative correlation with insulin resistance." (PMID 36381082, 2022). "Lastly, adults with NAFLD and insulin resistance show an impaired response to FGF19 compared to those with NAFLD and without insulin resistance." (PMID 35116006, 2021).
cholestasis (34 papers, 2013 to 2025). Impairment of the bile flow caused by obstruction within the liver, or outside the liver in the bile duct system. "Malabsorption of bile acids and dysfunction of farnesoid-X receptor (FXR)/fibroblast growth factor-19 (FGF19) axis worsen cholestasis and liver fibrosis." (PMID 40149924, 2025). "We also found that the administration of recombinant protein FGF19 also reversed vancomycin‐induced cholestasis and fibrosis by suppressing the expression of CYP7A1." (PMID 39680750, 2025). "The high expression of FGF19 in pig hepatocytes in this study indicated that pregnant sows are a promising animal model for the investigation of the pathogenesis of cholestasis during pregnancy." (PMID 35742938, 2022). "Together with the high relative expression of FGF19 in pig primary hepatocytes, pregnant sows are a promising animal model to investigate the pathogenesis of cholestasis during pregnancy." (PMID 35742938, 2022). "Together with the high relative expression of FGF19 in pig hepatocytes, the pregnant sow is a promising animal model to investigate the pathogenesis of cholestasis during pregnancy." (PMID 35742938, 2022). "A strong correlation exists between FGF19, and the severity of cholestasis, FGF19, and synthesis of BA was detected in patients with PBC-AIH OS." (PMID 32626734, 2020). "Synthesis of bile acids (BAs) plays an important role in liver injury in cholestasis, and the process is regulated by fibroblast growth factor 19 (FGF19)." (PMID 32626734, 2020). "During cholestasis, high levels of bile acids favor fibroblast growth factor 19 (FGF-19) expression." (PMID 32318580, 2020). "This study suggests that serum FGF19 levels increase proportionally in response to the degree of cholestasis and severity of the disease in PBC-AIH OS patients." (PMID 32626734, 2020). "Circulating FGF19 primarily controls the regulation of BA synthesis in response to cholestasis and under cholestatic conditions." (PMID 32626734, 2020). "In the physiological conditions, FGF19 is mainly released by the ileum; however, in cholestasis, this hormone is also produced in the liver." (PMID 32565779, 2020). "In accordance with the decrease in FGF19 in patients with cholestasis, BA-synthesized enzymes, including CYP7A1, CYP8B1, and CYP27A1, increased significantly in the liver." (PMID 30504803, 2018). "Analyses of the relationships between circulating FGF19, BA synthesis and cholestasis revealed that circulating FGF19 was strongly correlated with BA synthesis (r = -0.735, p<0.0001) and the severity of cholestasis (r = 0.590, p<0.001)." (PMID 28570655, 2017). "The analysis of the relationships between circulating FGF19, BA synthesis, cholestasis and prognosis presented in this report further an understanding of PBC pathophysiology and support the therapeutic potential of blocking hepatic BA synthesis." (PMID 28570655, 2017). "A previous report showed a correlation between serum and liver levels of FGF19 protein and severity of cholestasis in PBC." (PMID 27696157, 2017). "In contrast, BA synthesis seems to play a significant role in hepatic injury under cholestatic conditions, as suppression of hepatic BA synthesis following administration of an engineered form of FGF19 led to dramatic protection of the liver from cholestasis." (PMID 28570655, 2017). "In conclusion, our findings demonstrate that circulating levels of FGF19 are proportionally increased in response to the degree of cholestasis in patients diagnosed with PBC." (PMID 28570655, 2017). "The strong correlations between serum FGF19 and C4 and the degree of cholestasis, as indicated by bilirubin and TBA, further support this notion." (PMID 28570655, 2017). "Experimental study indicated that administration of FGF19 protected the liver from cholestasis by reducing hepatic synthesis and primary hydrophobic BA30." (PMID 27976737, 2016).
cholestasis (continued). "It is assumed that hepatic and biliary FGF19 supports endogenous bile acid suppression in cholestasis via autocrine and paracrine mechanisms." (PMID 27134744, 2016). "Further studies conducted in more patients with biopsy-proven steatosis, portal inflammation, and histological cholestasis or with different fibrosis stages are warranted to analysis relationship between them and FGF19." (PMID 27976737, 2016). "Secondly, It demonstrated that the altered FXR/FGF19 signaling was contributed to the cholestasis and liver injury in pediatric IF patients." (PMID 27976737, 2016). "Our study suggests that a combination treatment of FGF19 analog and Gly-βMCA may have clinical implications in conditions where cholestasis patients potentially benefit from enhanced reduction of bile acid pool size and hydrophobicity." (PMID 41202881, 2025). "Here, we test combination therapies of intestinal ASBT inhibition together with obeticholic acid (OCA), cilofexor, and the non-tumorigenic fibroblast growth factor 15 (Fgf15)/fibroblast growth factor 19 (FGF19) analogue aldafermin in a mouse model of cholestasis." (PMID 38074508, 2024). "Furthermore, fibroblast growth factor 19 (FGF19) was found in the liver samples from patients with cholestasis." (PMID 37261338, 2023). "However, the high levels of FGF‐19 are probably insufficient to counteract the increased serum bile acids pool due to the cholestasis." (PMID 31925905, 2020). "Our assessment of the correlations between serum FGF19, synthesis of BA, cholestasis, and prognosis advances our understanding of the pathophysiology of PBC-AIH OS and allows the potential therapeutic benefits of suppressing hepatic BA synthesis to be evaluated." (PMID 32626734, 2020). "Correspondingly, the serum FGF19 levels decreased significantly in patients with cholestasis." (PMID 30504803, 2018). "Our study showed that, in prolonged cholestasis, hepatocytes are an important source of FGF19." (PMID 26293907, 2015). "As such, combination of ASBT inhibitors with FGF19 agonists may be a therapeutic way to pharmacologically mimic total biliary diversion and thus provide another rationale to combine new anticholestatic drugs to eventually heal cholestasis." (PMID 27134744, 2016). "We previously showed in PN-fed neonatal pigs a disruption of bile acid-mediated activation of intestinal NR1H4-FGF19 signaling and that replacement with enteral CDCA restored FGF19 secretion and reduced serum markers of cholestasis." (PMID 41043692, 2025). "Parenteral nutrition-induced cholestasis disrupts bile acid-mediated activation of intestinal FXR-FGF19 signaling, and we showed that treatment with enteral chenodeoxycholic acid (CDCA) restored FGF19 secretion and reduced serum cholestasis in neonatal pigs." (PMID 41043692, 2025). "In contrast to experimental cholestasis, where a treatment usually elicits a more homogenous response, it is known that human cholestasis varies greatly in response to UDCA, FGF19 analog, or ASBT inhibitor treatment." (PMID 41202881, 2025). "We previously showed in PN-fed neonatal pigs a disruption of bile acid-mediated activation of intestinal FXR-FGF19 signaling and that replacement with enteral CDCA restored FGF19 secretion and reduced serum markers of cholestasis." (PMID 39282416, 2024). "Studies in TPN-fed neonatal piglets showed that the suppression of biliary flow leads to reduced circulating FGF19 and that enteral administration of the bile acid, chenodeoxycholic acid, a potent FXR agonist, increased plasma FGF19 and prevented cholestasis." (PMID 33557154, 2021). "The level of an important FXR target gene, FGF19, which is essential to the intestine-driven repression of hepatic CYP7A1, was reduced significantly in the serum of patients with cholestasis." (PMID 30504803, 2018). "FGF19, secreted by the ileum and upregulated in the human liver during cholestasis is an important negative feedback regulator of bile acid synthesis in humans." (PMID 40015320, 2025).
cholestasis (continued). "Fibroblast growth factor 19 (FGF19) analogue and inhibitors of the gut bile acid uptake transporter apical sodium-dependent bile acid transporter (ASBT) have been investigated as potential new therapeutics for cholestasis." (PMID 37408204, 2023). "Part of the beneficial effects of FXR agonists in cholestasis may be attributed to FXR-dependent induction of FGF19, and selective activation of FXR in the intestine even suggests that induction of ileal FGF19 may sufficiently treat cholestasis." (PMID 27134744, 2016). "Here we analyzed hepatic expression of FGF19 and other genes relevant to the adaptive response to cholestasis in tissues from non-cirrhotic (n = 24) and cirrhotic (n = 21) patients along with control tissues (n = 21)." (PMID 26293907, 2015). "Selective activation of FXR in the intestine protects mice against cholestasis by activation of FGF15 (mouse ortholog of FGF19) via a negative feedback loop to hepatic bile acid synthesis." (PMID 25093717, 2014). "Selective activation of FXR in the intestine protects mice against cholestasis by activation of FGF15 (mouse orthologue of FGF19) via a negative feedback loop to hepatic bile acid synthesis." (PMID 25093717, 2014). "Thus our work provides novel observation as no prior studies have analysed FGF19 expression in the intestinal tissue of patients with cholestatic diseases and prior data come mostly from animal models of cholestasis." (PMID 28008998, 2016). "Future strategies which combine the effects of the most powerful drugs to induce bicarbonate-rich choleresis, such as NorUDCA, with the most powerful drugs to suppress bile acid pool size, such as FGF19 mimetics or ASBT inhibitors, may therefore have real potential to heal cholestasis." (PMID 27134744, 2016). "This may suggest that increased liver expression of FGF19 is not restricted to PBC but represents a more universal mechanism in response to cholestasis." (PMID 26293907, 2015). "Although FGF19 is not expressed in hepatocytes and systemic FGF19 under physiologic conditions originate from the intestine, its hepatocellular expression is highly induced in cholestasis." (PMID 23540496, 2013). "Moreover, FGF19 treatment protected mice from CBDL-induced liver injury, whereas selective intestinal FXR overexpression decreased liver injury in the genetic Mdr2 knockout mouse model of cholestasis, confirming the importance of intestinal FXR for liver disease." (PMID 23540496, 2013). "FGF-19 modulator aldafermin may also be a promising drug for second-line PBC treatment, which improves cholestasis without pruritus worsening." (PMID 40783513, 2025). "We alternatively considered the possibility that the difference in FGF19 response between PSC and PBC patients may be disease-specific, rather than related to differences in severity of cholestasis." (PMID 27696157, 2017).
breast cancer (33 papers, 2010 to 2026). A primary or metastatic malignant neoplasm involving the breast. "FGF19 expression is elevated and is associated with a significantly shorter life expectancy of breast cancer patients of Saudi and Libyan descent." (PMID 25951871, 2015). "All these findings highlight the significance of FGF19/FGFR4 in treatment resistance phenomenon in breast cancer; thus, more thorough studies are necessary to explore the clinical significance of the FGF19/FGFR4 axis to improve patient outcomes." (PMID 39796710, 2024). "It is also mentioned that FGFR4 is a target for patients with breast cancer due to the co-expression of FGFR4 and FGF19, associating it with the expression of phosphorylated AKT." (PMID 38540215, 2024). "The human FGF19 gene is amplified in breast cancer together with FGF3 and FGF4, and this correlates with worse prognosis in invasive ductal breast carcinomas, particularly in older patients with lymph node metastasis and negative ER status." (PMID 35193394, 2022). "Genetic knock-out of FGF19 decreases breast tumour progression and metastasis in either mouse models of breast cancer or experimental metastasis models." (PMID 35193394, 2022). "Treatment of high-expressing FGF19 or FGFR4 positive breast cancer cells with an antibody against FGF19 or siRNA to FGF19 sensitizes the cells to doxorubicin." (PMID 32154250, 2020). "The amplification of the FGF19 gene was found in liver cancer, breast cancer, lung cancer, bladder cancer, head and neck squamous cell carcinoma (HNSCC), and esophageal cancer." (PMID 30634399, 2019). "FGF19 is one of its another nearby gene, and FGF19 and its receptor FGFR4 were strongly associated with the basal-like subtype of breast cancer." (PMID 31921621, 2019). "The SNP rs614367 is located in an intergenic region with multiple flanking genes, including CCND1, MYEOV, ORAOV1, FGF19, FGF4 and FGF3, all of which are potential breast cancer susceptibility genes." (PMID 30247654, 2019). "We next sought to test the potential benefit of targeting FGF19 therapeutically in breast cancer cells that co-express FGFR4 and FGF19." (PMID 27192118, 2016). "In summary, our results demonstrate that the FGFR4/FGF19 autocrine signaling mediates the survival of a subset of basal-like breast cancer cells through activation of PI3K/AKT signaling." (PMID 27192118, 2016). "As such, targeting the FGFR4/FGF19 autocrine loop represents a potential therapeutic strategy for future management of refractory basal-like breast cancers." (PMID 27192118, 2016). "The transcriptome biomarker profile, which includes the leucine zipper putative tumor suppressor 1, fibroblast growth factor receptor substrate 2, cyclin I, the EGF receptor, FGF-19, B-Raf gene, and growth regulation by estrogen in breast cancer 1, has been identified." (PMID 41245374, 2025). "Moreover, the FGF19/FGFR4 axis is suggested to play a critical role in treatment resistance in breast cancer." (PMID 39796710, 2024). "Co-expression of FGFR4 and FGF19 was observed in about 30% of primary breast cancers." (PMID 32154250, 2020). "Moreover, in breast cancer, autocrine FGF19/FGFR4 signaling is important for cell survival, and FGF19/FGFR4 co-expression was observed in primary breast tumors." (PMID 33066597, 2020). "We also measured three key pro-tumorigenic growth and angiogenic factors associated with inflammation, TGF-α, FGF-19, and HGF, and showed that both TGF-α and FGF-19 exhibited increased levels in both breast cancer and dense breast tissue compared with their normal tissue counterparts." (PMID 29387062, 2017). "Together, our results implicate that FGFR4 and FGF19 autocrine signaling may serve as a potential therapeutic target for the treatment of refractory basal-like breast cancers." (PMID 27192118, 2016). "Importantly, a subset of basal-like breast cancer cells also secrete fibroblast growth factor 19 (FGF19), a canonical ligand specific for FGFR4." (PMID 27192118, 2016).